LMBRD1 (LMBR1 domain containing 1)
Description:
Lysosomal membrane chaperone required to export cobalamin (vitamin B12) from the lysosome to the cytosol, allowing its conversion to cofactors. Targets ABCD4 transporter from the endoplasmic reticulum to the lysosome. Then forms a complex with lysosomal ABCD4 and cytoplasmic MMACHC to transport cobalamin across the lysosomal membrane. Acts as an adapter protein which plays an important role in mediating and regulating the internalization of the insulin receptor (INSR) (By similarity). Involved in clathrin-mediated endocytosis of INSR via its interaction with adapter protein complex 2 (By similarity). Essential for the initiation of gastrulation and early formation of mesoderm structures during embryogenesis (By similarity). [Isoform 3]: (Microbial infection) May play a role in the assembly of hepatitis delta virus (HDV).
Synonyms: LMBD1; C6orf209; NESI; FLJ11240; bA810I22.1; cblF; MAHCF
Tractability: Antibody: UniProt places it where antibodies can reach, with medium confidence; UniProt predicts a signal peptide or a membrane-spanning region; its Gene Ontology location is reachable by antibodies, with medium confidence. PROTAC: ubiquitination databases record sites on it; its protein half-life has been measured.
Gene: Protein-coding gene on chromosome 6 (69,672,757 to 69,867,236, reverse strand). Ensembl gene ENSG00000168216.
Subcellular location: Endoplasmic reticulum membrane; Lysosome membrane; Cell membrane; Cytoplasmic vesicle, clathrin-coated vesicle
Subcellular location (Human Protein Atlas): Vesicles
Pathways (Reactome):
Metabolism: Transport of RCbl within the body; Uptake of dietary cobalamins into enterocytes
Disease: Defective ABCD4 causes MAHCJ
Gene Ontology:
Molecular function: ABC-type vitamin B12 transporter activity; protein binding; vitamin transmembrane transporter activity; AP-2 adaptor complex binding; clathrin heavy chain binding; insulin receptor binding
Biological process: protein localization to lysosome; clathrin-dependent endocytosis; gastrulation; insulin receptor internalization; cobalamin transport; vitamin transmembrane transport
Cellular component: endoplasmic reticulum membrane; lysosomal membrane; membrane; clathrin-coated endocytic vesicle; clathrin-coated vesicle; plasma membrane; lysosome
Genetic constraint (gnomAD): Loss-of-function variants: 33 observed, 37.28 expected, observed/expected ratio (o/e) 0.89, 90% interval 0.67 to 1.18. The upper end of that interval is the gene's LOEUF score, 1.18, which puts it in group 5 of 6, group 1 being the genes least tolerant of losing a copy. Missense variants: 382 observed, 393.05 expected, observed/expected ratio (o/e) 0.97, 90% interval 0.89 to 1.06. Synonymous variants: 121 observed, 137.36 expected, observed/expected ratio (o/e) 0.88, 90% interval 0.76 to 1.02.
Gene-disease validity (ClinGen):
ClinGen rates the evidence that LMBRD1 causes each of these diseases.
methylmalonic aciduria and homocystinuria type cblF (autosomal recessive): Definitive.
Homologues: Orthologues: chimpanzee LMBRD1 (99% identical), macaque LMBRD1 (99% identical), guinea pig LMBRD1 (95% identical), rabbit LMBRD1 (94% identical), mouse Lmbrd1 (93% identical), rat Lmbrd1 (93% identical), pig LMBRD1 (92% identical), zebrafish lmbrd1 (74% identical), tropical clawed frog lmbrd1 (69% identical).
Diseases named in the same sentence as LMBRD1 in open-access papers:
LMBRD1 is named in the same sentence as 24 diseases in open-access papers, as found by Europe PMC text mining. Sharing a sentence is not in itself a finding about the gene and the disease. The quoted sentences say what the papers report.
homocystinuria (12 papers, 2015 to 2025). An autosomal recessive inherited metabolic disorder caused by mutations in the CBS, MTHFR, MTR, and MTRR genes. "In particular, mutations in LMBRD1, ABCD4, and MMACHC genes (corresponding to cblF, cblJ, and cblC complementation groups) are associated with combined methylmalonic aciduria and homocystinuria." (PMID 38203763, 2024). "LMBRD1 (LMBR1 domain containing protein 1) is associated with autosomal recessive methylmalonic aciduria and homocystinuria (cobalamin F type; cblF type)." (PMID 35474353, 2022). "LMBRD1 has been associated with methylmalonic aciduria and homocystinuria (cblF disorder, OMIM #277380)." (PMID 35474353, 2022). "Combined methymalonic aciduria and homocystinuria consists of four subtypes, MMACHC(cblC), MMADHC (cblD combined, cblD-MMA and cblD-HCY), LMBRD1(cblF) and ABCD4(cblJ)." (PMID 26149271, 2015).
Developmental delay (2 papers, 2016 to 2017). "Cobalamin F (cblF) disorder, caused by homozygous or compound heterozygous mutations in the LMBRD1 gene, is a recognised cause of developmental delay, pancytopaenia and failure to thrive which may present in the neonatal period." (PMID 26997947, 2016).
vitamin B12 deficiency (2 papers, 2016 to 2024). A disease characterized by low serum levels of vitamin B12, either inherited or acquired. "Thus, the single nucleotide polymorphism sites associated with decreased expression of the human LMBRD1 gene evaluation may not only indicate the cause of vitamin B12 deficiency but also prognose a risk of onset of cardiovascular diseases." (PMID 39125597, 2024).
folate deficiency (1 paper, 2019). A nutritional condition produced by a deficiency of FOLIC ACID in the diet. "B12 deficiency with either state of folate in comparison to control (BNFN) revealed that combination with folate normal (BDFN) as well as folate deficiency (BDFD) led to an increase in transcript levels of LMBRD1 in all fetal tissues." (PMID 31772242, 2019). "Comparing the effect of folate deficiency with either state of B12 in comparison to control, combination with B12 deficiency (BDFD) increased the LMBRD1 transcript in the liver and placenta whereas it was increased in the brain in BNFD group (BNFN vs BNFD, BDFD)." (PMID 31772242, 2019). "Condition of folate deficiency in combination with B12 deficiency (BDFD) resulted in a raised level of LMBRD1 gene all fetal tissues regardless of sex whereas combination with B12 over-supplementation (BOFD) showed such effects in the liver (male) only as compared to BNFN." (PMID 31772242, 2019). "Under the condition of B12 over-supplementation, the LMBRD1 mRNA levels were increased in combination with folate normal (BOFN) in all fetal tissues regardless of sex whereas, in combination with folate deficiency (BOFD), the expression was increased in the liver (male) as compared to BNFN." (PMID 31772242, 2019).
oncocytoma (1 paper, 2024). "In a study aimed at distinguishing ChRCC from RO, the genes LMBRD1, TPBG, MANEA, and HACE1 were integral components of a 30-gene signature known as chromophobe and oncocytoma-related gene signature (COGS)." (PMID 39684226, 2024).
schizophrenia (1 paper, 2013). A major psychotic disorder characterized by abnormalities in the perception or expression of reality. "Moreover, we also found a significant association between LMBRD1 gene and schizophrenia in our Taiwanese family samples of schizophrenia." (PMID 23555897, 2013). "In addition, the LMBRD1 knockout mouse model revealed a neurological impairment and manifested a prominent social withdrawal behavior, representing the negative symptom state of schizophrenia." (PMID 23555897, 2013).
tumor (1 paper, 2021). "In addition, we observe that four genes (i.e., COL9A1, MSANTD2, LMBRD1 and RP11-1391J7.1) were differentially expressed between normal samples and tumor samples, and that COL9A1 was differentially expressed among different tumor stages." (PMID 34627275, 2021).
LMBRD1 also shares sentences with these, for which no sentence is quoted: Methylmalonic aciduria (5 papers); metabolic disease (2); adrenoleukodystrophy (1); Alzheimer disease (1); biotinidase deficiency (1); cardiomyopathy (1); cardiovascular diseases (1); dilated cardiomyopathy (1); Failure to thrive (1); GM2 gangliosidosis (1); hepatoma (1); Insulin resistance (1); pancytopaenia (1); renal agenesis (1); Situs inversus totalis (1); Transcobalamin deficiency (1); Ventricular hypertrophy (1).